BRCA1 (BRCA1 DNA repair associated)
Diseases named in the same sentence as BRCA1 in open-access papers (continued):
Sharing a sentence is not in itself a finding about the gene and the disease.
cancer (continued). "Therefore, pathogenic variants in BRCA1 or BRCA2 can disrupt important biological functions, allowing the accumulation of genetic alterations and consequently increasing cancer susceptibility." (PMID 32087690, 2020). "In one of the studies, in individuals who underwent multigene testing, the researchers found that 3.8% of BRCA1/2 mutation-negative individuals harbored deleterious mutations in other hereditary cancer predisposition genes." (PMID 33552952, 2020). "Here, we show that fork degradation is no longer detectable in BRCA1-deficient cancer cells exposed to multiple cisplatin doses, mimicking a clinical treatment regimen." (PMID 31676232, 2020). "Our analysis revealed a mutation rate of 11.11% (6/54) in other cancer predisposition genes beyond BRCA1/2 in non-BRCA carriers, which was only slightly lower than that in the germline BRCA1/2 mutation carriers [14.19% (21/148)] in TNBC." (PMID 33194720, 2020). "We screened the human ENCODE database for cancer-associated TFs that interact with BRCA1 promoter in four of commonly used cancer cell lines (GM12878, K562, HepG2, and Hela-S3) and identified dozens of TFs that are associated with the BRCA1 promoters." (PMID 32000125, 2020). "Due to its broad anti-tumor efficacy in most solid tumors, this novel combination therapy should be applicable to other cancer stem cells and tumors; 2) PARPi-ionizing radiation (IR) combination; Nuclear localization is required for BRCA1 to participate in HR-mediated DNA repair." (PMID 32563252, 2020). "Regarding BRCA1/2 mutational status, for none of the miR-34 family members a different expression between wild-type and mutated cancers was found." (PMID 32047551, 2020). "In a subgroup analysis stratified according to BRCA1/2 mutation carrier status, the F352V polymorphism was associated with the overall cancer risk in BRCA1 mutation carriers but not in BRCA2 mutation carriers." (PMID 32585905, 2020). "In addition, it is well known that BRCA1-defective cancers are intrinsically sensitive to poly (ADP-ribose) polymerase (PARP) inhibition." (PMID 32451425, 2020). "Also, epigenetic changes of BRCA1 induce a CAF-like state in fibroblasts from healthy tissues, increasing cancer predisposition." (PMID 32842712, 2020). "The results of our study suggest that BRCA1 (but not BRCA2)-mutated women with no history of cancer have an independent reduction in the response to ovarian stimulation." (PMID 31872386, 2020). "In a follow-up study devoted to target validation and further mechanistic insights into CuET effects, we explored the reported exceptional sensitivity to DSF of human cancer cell lines defective in BRCA1 or BRCA2 tumor suppressors, key components of the genome integrity maintenance machinery." (PMID 32085572, 2020). "In order to develop assays for functional characterization of cancer-associated variants located in BRCA1 and BRCA2, yeast strains overexpressing full length BRCA1 or BRCA2 under the control of a constitutive (pADH) or inducible promoter (pGAL1) have been constructed." (PMID 32656256, 2020). "One such example includes a combination therapy of rucaparib and temozolomide in metastatic melanoma, a cancer not typically associated with BRCA1/2 mutations." (PMID 32194409, 2020). "Effective non-surgical approaches for cancer risk-reduction in BRCA1 mutation carriers will likely come from thorough understanding of the mechanisms responsible for cancer predisposition in this population." (PMID 32120796, 2020). "Therefore, our research provided a clue to how mutations of BRCA1 and NSD2 resulted in cancer transformation." (PMID 32826945, 2020). "Moreover, BRCA1/2, ATM, and CHEK2 are the most frequently mutated DNA repair genes in somatic cancer cells." (PMID 32029455, 2020). "Women with a BRCA1/2 mutation and no previous cancer diagnosis were recruited from the United States, Canada, the United Kingdom, Australia and from a national advocacy group." (PMID 32393849, 2020).
cancer (continued). "For example, BRCA1-mutated tumor cells, which also harbor 53BP1 inactivations, show resistance to PARPi, while this phenotype depends on ATM activity, which makes these cancer cells specifically vulnerable to ATM inhibition." (PMID 33299637, 2020). "The 12.2% de novo germline mutation rate in MMR genes and other non-CRC cancer susceptibility genes (BRCA1, BLM, and NTHL1) reported herein for the young sporadic CRC group is reasonable and expectable." (PMID 33260537, 2020). "Because the frequency of BRCA1 and BRCA2 mutations in Indonesia are relatively low and the genetic tests were not widely available, our study did not specifically address the genetic risk for the development of bilateral cancer." (PMID 33204419, 2020). "Furthermore, a meta-analysis of BRCA1-related cancer revealed that all basal-like tumours belong to the TNBC subtype, much higher than the average level." (PMID 32591500, 2020). "BRCA1-deficient TNBCs are prone to poly(ADP-ribose) polymerase inhibitors (PARPi), whose action results in the deficient repair of DNA single-strand breaks (SSBs), which, when unrepaired, produce DSBs in replicating cancer cells." (PMID 32456160, 2020). "For women with pathogenic/likely pathogenic variants in BRCA1/2, some risk-reducing strategies, such as prophylactic surgeries, have demonstrated reduced cancer risk and mortality in some studies, but not others." (PMID 32090079, 2020). "It has been shown that PARPi cytotoxicity against BRCA1/2-deficient cancer cells correlates with their trapping potency and not with their inhibitor properties." (PMID 32784607, 2020). "Majority of the participants have a personal history of BRCA1/2-related cancer(s) (70%), a family history of cancer (91%) and had recently (< 1 year) learned their positive BRCA1/2 PV/LPV carrier status (45%), with a median of 1.8 years since GT result disclosure." (PMID 33110458, 2020). "Therefore, the unique molecular traits of each BRCA protein create a difference between BRCA1- and BRCA2-mutated cancers." (PMID 32269964, 2020). "Among 259 BRCA1 PV carriers, 116 individuals (44.8%) were patients with cancer diagnosis related to hereditary breast and/or ovarian cancer syndrome, 133 subjects (51.3%) were healthy and 10 individuals (3.9%) were excluded from the study for lack of sufficient information." (PMID 32380732, 2020). "The identification of the relevant role of BRCA1 and BRCA2 tumor suppressor genes in FA pathogenesis has solidly linked FA genetic background to DNA repair defect, and hence to cancer predisposition." (PMID 32962238, 2020). "While the cellular consequences of BRCA1-mutations are well characterized, the interaction between cancer cells lacking BRCA1 and their microenvironment is less studied." (PMID 32053991, 2020). "BRCA1 and/or BRCA2 mutations are frequently detected in both cancer types." (PMID 32250967, 2020). "In addition to very rare germline variants in genes related to liver function, such as HOXC4, PRSS56, and CYP1A1, the patient carried two variants strongly predicted to be deleterious affecting BRCA1 and FAH, both genes associated with cancer predisposition." (PMID 32432034, 2020). "However, in BRCA1 mutation carriers, BRCA1 haploinsufficiency-driven overexpression of RANK-L was observed, which correlated to the RANKL-addicted cancer stem cell-like behavior within cell populations with the BRCA1 mutation." (PMID 32883003, 2020). "Thus, maintenance of a normal level and integrity of BRCA1 protein in cells is crucial for the sustainment of normal cellular function and the prevention of cancer and neurodegeneration." (PMID 31963223, 2020). "We emphasize that we found BRCA1/2 mutations in 14.5% of OC patients with no family cancer history who would currently not be revealed presymptomatically without population screening." (PMID 32295079, 2020). "Interestingly, RAD18 promotes replication fork protection in BRCA1 mutant cancers through the PCNA-TLS pathway." (PMID 32182354, 2020).
cancer (continued). "Cancer-derived variants of BRCA1, BARD1, OLA1, and RACK1 failed to interact, and aberrant expression of these proteins caused centrosome amplification due to centriole overduplication only in mammary tissue-derived cells." (PMID 32722046, 2020). "However, BARD1 is also reported to be involved in BRCA1-independent oncogenic signalling modulation to facilitate cancer progression." (PMID 32719318, 2020). "Whereas many chronic diseases can currently be prevented (e.g., cardiovascular diseases), no recent tangible progress was made in cancer prevention of BRCA1 mutation carriers apart from surgical resections of at-risk organs." (PMID 32120796, 2020). "On the contrary, a study shows that 72.3% of participants among the BRCA1 variant carriers did not report any family history of cancer." (PMID 32856854, 2020). "High expression of CCNB1 was also observed in BRCA1-mutant cancer and induction of vinblastine targeting CCNB1 could significantly reduce tumor progression." (PMID 32716025, 2020). "However, in BRCA wilde-type cancers, an inverse correlation between the expression of BRCA1/2-mRNA and miR-34 b/c and between miR-34a and BRCA2 mRNA was pointed out." (PMID 32047551, 2020). "Other mutational signatures including SBS40, SBS5, ID9, ID1 and ID2 were not significantly enriched more in BRCA1/2-mutated cancers expressing wild-type POLQ than in other types of cancers." (PMID 32885167, 2020). "Eleven of the BRCA1/2 heterozygotes had other cancer diagnoses in their lifetime." (PMID 32300229, 2020). "The BRCA1 and BRCA2 (BRCA) genes encode key proteins in the homology-directed DNA break repair (HDR) pathway, and their inactivation predisposes individuals to cancer development." (PMID 32444794, 2020). "There are currently no prospectively validated non-surgical measures to prevent cancers of the reproductive tract in BRCA1 mutation carriers." (PMID 32120796, 2020). "The BRCA1 and BRCA2 genes encode proteins involved in double-stranded DNA break repair; thus, BRCA mutation-associated cancers may be more sensitive to chemotherapeutic agents that cause DNA damage, such as platinum-based agents." (PMID 32098267, 2020). "In a pan-cancer analysis of BRCA1 and BRCA2 genomic alterations using hybrid captured-based comprehensive genomic profiling, the fraction of BRCA1/2 altered biallelic cases was 68.7%, which is highly associated with elevated genome-wide loss of heterozygosity (gLOH)." (PMID 33324554, 2020). "Several evidence have confirmed that BRCA1 is a key regulator of Sirt1 in cancer research." (PMID 32381096, 2020). "In relation to tumorigenesis specifically related to BRCA1 and BRCA2, data suggest that BRCA bi-allelic inactivation renders the cell vulnerable to genomic instability, being the background for successive mutations that culminate in cancer development." (PMID 32481735, 2020). "The study defines features useful for identifying BRCA1- or BRCA2-deficient cancer types regardless of subtype." (PMID 32719318, 2020). "Although the presence of pathogenic variants in BRCA1 or BRCA2 is the best genetic predictor for a good clinical response to PARPi therapy, multiple studies have shown that PARPi efficacy is also observed in patients with non-BRCA1/2-deficient carcinomas." (PMID 33003546, 2020). "The multivariable analysis also showed a significant age-dependent decrease in risk of recurrence and cancer-related death in non-carriers but not in BRCA1/BRCA2 carriers." (PMID 31141992, 2019). "The information gained in this study could also be applied to different cancers because the BRCA1-mTORC2 interaction is broadly translatable." (PMID 31771139, 2019). "Indeed, PARP inhibition in BRCA1 or BRCA2‐defective cancer cells leads to increased levels of mitotic aberrancies including chromatin bridges and micronuclei." (PMID 31529615, 2019).
cancer (continued). "Notably, inactivation of the 53BP1-dependent resection barrier dramatically reduces the effectiveness of the treatment on BRCA1 defective cells, possibly leading to genome instability, poor prognosis, and cancer relapse." (PMID 31380392, 2019). "Given that, we reanalyzed the WES datasets including 10 familial non-BRCA1/BRCA2 BC pedigrees, manually evaluated variants as recommended, and performed data mining on pan-cancer datasets." (PMID 31214250, 2019). "Among the individuals with a pathogenic finding, 43.6% (126/289) of the alterations identified cases, the alteration identified occurred in the BRCA1 or BRCA2 genes, indicating the significant contribution of these two genes in hereditary cancer predisposition." (PMID 31159747, 2019). "For instance, though the familial breast cancer susceptibility gene 1 (BRCA1) mutations contributes to 5–10% of EOC, promoter hypermethylation of non-mutated BRCA1 allele is the second disruptive event to the development of this cancer." (PMID 31608277, 2019). "Paradoxically, PARP inhibitors were found to be effective in treating other types of cancers lacking BRCA1/2 mutations or defects in HR pathway." (PMID 30741937, 2019). "Interestingly, cancers that showed epigenetic silencing of BRCA1 (n = 32, 995) or RAD51C (n = 23, 995), or that carried germline PALB2 (n = 3, 995) or RAD51C (n = 1, 995) mutations, also displayed an increased contribution from CS-3." (PMID 31092228, 2019). "Thus, data assessing the predictive value of BRCA1 promoter methylation to incidental cancers (by collecting blood samples years prior to diagnosis) are lacking." (PMID 31225507, 2019). "Restoration of BRCA1 expression reverses HR‐mediated repair deficiency and allows the cells to repair the damage induced through PARP inhibition, and mutations that restore activity of other HR proteins have also been observed in PARPi‐resistant cancer cells." (PMID 30714316, 2019). "Study 42 is an open-label non-comparative single-arm phase II study that examined olaparib monotherapy in germline BRCA1/2-associated cancers, regardless of tumor type." (PMID 31032221, 2019). "LOH is observed in most cancers in BRCA1, BRCA2, and NBN carriers." (PMID 31614901, 2019). "Five mutated gene variants that were transferred to the BRCA1-KO fibroblasts (BTN3A2, DDX51, LARP6, AP1G1 and COL18A1) were found to be also present as RNA variants following RNA sequencing of BRCA1-KO fibroblasts after exposure to cancer EVs." (PMID 31200749, 2019). "It should be noted that patients from Group 4 were not tested for germline mutations in BRCA1/BRCA2 because of the criteria adopted by the Oncogenetics Department of Barretos Cancer Hospital." (PMID 31244284, 2019). "Recent studies demonstrated that RAD52 has an important role in genomic stability maintenance and cancer suppression in mammalian cells, while several HR proteins including BRCA1, BRCA2, PALB2, and RAD51 paralogs (RAD51B, C, D, and XRCC 2 and 3) present an inactivated and depleted activity." (PMID 31652722, 2019). "Clinical and familial features of cancer patients carriers of 9–12 del BRCA1." (PMID 31545835, 2019). "Somatic mutations may also arise in HRR-associated genes; however, germline mutations are more common than somatic mutations in BRCA1- and BRCA2- mutated cancers." (PMID 30934991, 2019). "Moreover, we sequenced the TruSight Cancer panel (Illumina, Inc.), which in addition to BRCA1/2 targets another 92 genes." (PMID 31029168, 2019). "This MEK inhibitor-based combination therapy showed potent anti-cancer effect in multiple cancer cell lines and mice models not limited to BRCA1/2 mutated cells." (PMID 31737426, 2019). "While BRCA1/2 variant-positive individuals had significantly increased risk of HBOC-related cancers, those with uncertain/conflicting variants did not, suggesting that many of these variants are likely to be benign or of low penetrance." (PMID 31892343, 2019).
cancer (continued). "In men however, BRCA1&2 related cancers are less prevalent and have better prognosis." (PMID 31489114, 2019). "Consequently, USP9X regulates BRCA1‐mediated HR repair and confers resistance to DNA‐damaging agents in human cancer cells." (PMID 31512408, 2019). "A positive BRCA1/2 gene test result impacts treatment choices in women diagnosed with cancer and risk management in women with and without a cancer diagnosis, including an uptake of risk-reducing surgeries." (PMID 31795362, 2019). "Among the 481 female patients, 135 patients were detected to carry pathogenic (P)/likely pathogenic (LP) mutations (28.1%), which corresponded to 12 different cancer predisposition genes [14.6% (70/481) on BRCA1 gene, 5.0% (24/481) on BRCA2 gene, 8.5% (41/481) on non‐BRCA1/2 genes]." (PMID 30982232, 2019). "Depletion of Pol θ in human cancer cells deficient in HRR due to absence of BRCA1/2 increases chromosomal aberrations and impaired cell survival." (PMID 31552165, 2019). "Oestrogen may act through the PI3K - protein kinase B (PKB, also known as AKT) - mammalian target of rapamycin (mTOR) pathway to induce NRF2 accumulation, supporting the emerging clinical strategy of treating BRCA1-related cancers with PI3K inhibitors." (PMID 30915162, 2019). "This supports that most of BRCA1-related cancers belong to the basal-like subtype." (PMID 31307407, 2019). "Olaparib is a PARP-inhibitor approved for clinical use in BRCA1- and BRCA2- deficient cancers." (PMID 31847370, 2019). "Since RD‐N induced BRCA1 degradation through CTSB, we sought to determine whether down‐regulation of BRCA1, which is critical in maintaining genomic integrity by promoting homologous recombination (HR), would affect RD‐N mediated apoptosis of cancer cells." (PMID 30565390, 2019). "Furthermore, a study evaluating the coding regions and exon-intron boundaries of a 42-cancer gene sequencing panel (including BRCA1 and BRCA2) identified one or more VUS in approximately 90% of the patients." (PMID 30696104, 2019). "Notably, in a recent study using a low detection limit, Peplonska and colleagues detected evidence of WBC BRCA2 and BRCA1 methylation in 18.3% and 21.5%, respectively, among (presumably) cancer-free participants." (PMID 31225507, 2019). "Future examination of R-loops in cancer models should determine whether the seemingly independent functions of BRCA1 and BRCA2 are coordinated to prevent RF collapse through FANC-complex-mediated mechanisms." (PMID 31225499, 2019). "BRCA1, BRCA2, PALB2 variants are also associated with increased risk of ovarian and other cancers." (PMID 35582724, 2019). "Thus, cancer cells carrying HR DNA repair molecular alteration, like BRCA1/2 defects, are selective target of the PARP inhibition, resulting in a synthetic lethal phenotype." (PMID 31877762, 2019). "Current strategies for female BRCA1 and BRCA2 mutation carriers to manage the elevated cancer risk include an intensified breast screening program (including magnetic resonance imaging, breast ultrasound, mammography, and breast palpation by a physician) as well as risk-reducing surgeries." (PMID 31370837, 2019). "Notably, the knowledge of a BRCA1/BRCA2 mutation is likely to significantly change the assessment of a DCIS patient's risks for future cancers and the cancer prevention/risk reduction recommendations that would be considered." (PMID 30652428, 2019). "Thus, we confined the study population to those who received germline BRCA1/2 gene testing at the time of or within 2 years from cancer diagnosis to minimize survival bias." (PMID 31064392, 2019).